IL10 (interleukin 10)
Diseases named in the same sentence as IL10 in open-access papers (continued):
Sharing a sentence is not in itself a finding about the gene and the disease.
depression (continued). "A grouped meta-analysis found significant positive associations between concentrations of TNF-a, IFN-γ, IFN-γ PHA, IL-10, IL-10 (LPS and PHA), IL-6, IL-6 (LPS and PHA) and levels of depression in individuals with MS." (PMID 39867847, 2025). "This analysis exhibited several cytokines and receptors, including IL10, CXCL9, and CXCR4, as key components in the relationship between depression and immunotherapy efficacy." (PMID 40761787, 2025). "The other cytokines measured—IL-1β, IL-4, IL-10, and TNF-α—showed little variation throughout the different phases, indicating their minimal involvement in the mediation of depression." (PMID 40564108, 2025). "Folic acid, a medication used for pregnancy, promoted astrocytic IL-10 expression by inhibiting EZH2-mediated H3K27me3 and improved depression-like behaviors in adult mice." (PMID 40108901, 2025). "The aim of the paper was to analyze the relationship between somatization in elderly patients with major depressive disorder (MDD) and brain-derived neurotrophic factor (BDNF), IL-6, IL-10, and TNF-a cognitive function, and sleep quality (SQ)." (PMID 40821647, 2025). "In animal models of depression, increased levels of pro-inflammatory cytokines, such as IL-1β and TNF-α, and decreased levels of anti-inflammatory cytokines, such as IL-10 and TGF-β1, have been observed in the hippocampus and cortex." (PMID 38575920, 2024). "Conventional antidepressants, such as sertraline and fluoxetine, result in the upregulation of anti-inflammatory cytokine IL-10 and decrease the production of IFN-γ and thus are effective at reducing anxiety-like and depression-like symptoms in patients." (PMID 38791125, 2024). "IL-10 expression was inhibited in the CUMS model, and increased levels of IL-1β, IL-6, and TNF-α were observed in the sera of the CUMS mice with depression-like behaviors." (PMID 38378622, 2024). "In another study, family history of depression, third semester cortisol AUC, and third semester IL8/IL10 predicted symptoms of PPD." (PMID 38820411, 2024). "The effectiveness of the treatment was evaluated by the Hamilton Depression Scale (HAMD-17), Self-Depression Scale (SDS), Modified Barthel Index Score (MBI), and the serum levels of IL-1β, IL-6, IL-10, TNF-α, and INF-γ." (PMID 38370556, 2024). "Treatments, including RSNP, crocin-1, and an enriched environment, increased IL-10 in the HPC, which attenuated depression-like behaviors." (PMID 38791125, 2024). "TNFα, IL-10, and MCP-1 (CCL2), biomarkers of inflammation, are also increased in people with depression." (PMID 39337564, 2024). "Clinical studies have found that patients with IBS and depression have higher levels of TLR4 expression and IL-6, accompanied by a decrease in IL-10, which indicates that TLR participates in the inflammation reaction in IBS and depression." (PMID 39749341, 2024). "For instance, a study on adolescent patients with the first-episode of depression highlighted a correlation between pro-inflammatory TNF- and IL-6 signaling and increased anti-inflammatory activity mediated by IL-10 and IL-4." (PMID 38912378, 2024). "Reduced levels of cytokines such as IL-10, IL-4, and TGF-β1 have been observed in both the plasma of patients with depression and the brain tissue of animal models of depression." (PMID 38916735, 2024). "The results revealed that depression patients’ plasma levels of CCL2, IL-6, IL-4 and IL-10 were all positively correlated." (PMID 37575572, 2023). "Furthermore, IL-6, tumor necrosis factor-alpha (TNF-α), and IL-1β are implicated in the pathophysiology of depression, and individuals with depression often have elevated circulating IL-1β, IL-6, and TNF with reduced levels of interferon-gamma (IFN-γ), IL-10, and IL-4." (PMID 35546876, 2022). "Faecalibacterium prausnitzii administration increases the IL-10 level and reduces IL-6 as well as CORT levels in depression-like and anxiety-like rats." (PMID 35744601, 2022).
depression (continued). "Previously, it was shown that, in RA, IL-10 levels are positively correlated with RF, anti-CCP, and CRP, while there is also a well-established link between depression and elevated IL-10." (PMID 35330475, 2022). "The levels of IL-4, IL-10, T, and NPY in depression patients, DCMI patients, and CUMS + LPS model rats elevated, while the levels of IL-1β, IL-6, and TNF-α were reduced." (PMID 35432561, 2022). "We also examined the mRNA level of inflammation-related factors, including IL-1β, IL-6, TNFα, and IL-10 in the PFC, dorsal hippocampus, and ventral hippocampus, which are three critical regions of the brain that are related to anxiety and depression." (PMID 35684068, 2022). "The findings in this study do not support a role of CNS inflammation, as measured by altered CSF levels of IL-6, IL-8, TNF-α, IL-10, MCP-1 or TGF β, in geriatric patients with depressive disorders." (PMID 36172507, 2022). "We found several consistent risk factors for CIPN including more severe baseline neuropathy, more severe fatigue/anxiety/depression, higher levels of pro-inflammatory IFN-γ, and lower levels of anti-inflammatory IL-10, and black race." (PMID 34191201, 2021). "IL-10 and MOR have a depression relationship, suggesting that, in addition to the possible correlation between immune and opioid systems, mood triggers such an interaction." (PMID 34099024, 2021). "In the present study, mother’s depression and PM2.5 exposure were independent predictors of IL-10 concentrations." (PMID 34064967, 2021). "Younger adults suffering from depression present a significant decrease in the peripheral levels of IL-6, TNF-α, IL-10, and MCP1 after pharmacological treatment with antidepressants." (PMID 35002817, 2021). "For IL-10 only, effects of PM2.5 and depression appeared to be additive, as depression had a significant, independent effect on cytokine concentrations." (PMID 34064967, 2021). "In in vitro and in vivo models of depression, BDNF was shown to improve depressive-like behavior by upregulating anti-inflammatory cytokine IL-10, IL-4, and TGF-β1 and downregulating the pro-inflammatory cytokine IL-1β, IL-17, and TNF-α." (PMID 32256638, 2020). "STAT3 is one of the transcription factors regulating the production of the cytokine IL-6, IL-10, TNF-α, and IL-1β, which have been shown to be involved in depression." (PMID 32655424, 2020). "Increases in serum pro- and anti-inflammatory cytokines have been observed in patients with depression, such as IL-1β, IL-6, and TNF-α, and IL-10, respectively." (PMID 30678337, 2019). "Increases in biomarker levels were correlated with reduction in depression severity for TNF-α, IL-6 IL-10 and CRP." (PMID 31375659, 2019). "We also found that positive changes in TNF-α, IL-6, IL-10 and CRP levels significantly correlated with higher reduction in depression symptoms." (PMID 31375659, 2019). "ICV application of these cytokines provokes anxiety- and depression-like behaviors, whereas the ICV application of IL-10, an anti-inflammatory cytokine, abolished these behaviors." (PMID 30208926, 2018). "Compared to IL-6, reports indicated that the relationships between depression and TNF-α, IL-12 and IL-10 are few." (PMID 30400354, 2018). "The sex difference in the association between maternal immune activity and offspring's risk of depression was because of sex-dependent variation in TNF-α relative to IL-10, and, therefore, we speculate the inability of the mother to mount an anti-inflammatory (IL-10) response to adverse stimuli." (PMID 27244231, 2016). "Secondary outcomes include serum biomarkers of SCI osteoporosis (sclerostin, P1NP and β-CTX), markers of immune function (IL-6, IL-10, FGF2, INF-γ, TNF-α), neurological function, body composition, depression and quality of life." (PMID 25563584, 2015).
depression (continued). "The investigated pro- and anti-inflammatory cytokines TNF, IL-6, IL-8, and IL-10 as well as DOR were expressed in skin from the upper and lower leg of patients with FMS, depression, and healthy controls." (PMID 25240423, 2014). "Depression and anxiety were analyzed using the Hospital Anxiety and Depression Scale (HADS), and serum levels of IL-1β, IL-6, IL-8, IL-10, IL-12, TNF-α, and TGF-β were measured by Cytometric Bead Array." (PMID 25309921, 2014). "Likewise, risk of depression following stroke was enhanced among individuals who carried alleles associated with reduced anti-inflammatory cytokine functioning (IL-4 and IL-10 gene polymorphisms), although no such association was found with respect to pro-inflammatory cytokine polymorphisms." (PMID 23675319, 2013). "Depression exerts bidirectional effects on CCS through 2 immune pathways, IL-10 (negative causal effect, 34.20%) and TRAIL (positive causal effect, 7.38%)." (PMID 41327674, 2025). "The correlation between levels of depression and IL-10 PHA was not significant, r = 0.26, 95% CI [-0.05,0.58], p = .099." (PMID 39867847, 2025). "Overall, the findings of these studies suggest that a range of cytokines, including IL-6, IL-10, TNF-α, and IL-8, may be involved in the pathophysiology of depression and that further research is needed to understand their roles fully." (PMID 40821647, 2025). "The correlation between levels of depression and IL-10 LPS was not significant, r = 0.29, 95% CI [-0.04,0.63], p = .085." (PMID 39867847, 2025). "The difference between IL-6 and IL-10 levels in women with and without depression was not statistically significant." (PMID 40682534, 2025). "Some studies have shown no change in IL-10 in patients with SCZ or depression, whereas others have shown that IL-10 is elevated in patients with mental disorders." (PMID 40292283, 2025). "Several depression-related cytokines including CCL2, IL-6, and IL-10 were significantly increased." (PMID 39409106, 2024). "Although IL-10 as a neuroinflammatory factor is involved in depression, the transcriptional regulatory mechanism of IL-10 in the microglia has not been elucidated." (PMID 38822367, 2024). "In a mouse model of depression, microglial but not peripheral blood IL-10 levels were reduced in learned helplessness mice; administration of IL-10 improved procognitive actions in learned helplessness mice or mice with cognitive impairments." (PMID 39358787, 2024). "The researchers revealed a negative correlation between IL-10 levels and Hamilton rating scale for depression (HAMD) scores, and suggested that IL-10 can be used as a predictor for predicting PSD at a 1-month follow-up." (PMID 38421829, 2024). "A case–control study involving patients with MDD and individuals without depression showed that the patients with MDD exhibited higher levels of plasma IL-10." (PMID 39358787, 2024). "There is less evidence for altered levels of IL-10 in PD patient CSF, but CSF levels of IL-10 were found to correlate with non-motor symptoms of depression and anxiety in PD patients." (PMID 38059210, 2023). "Plasma levels of IL-1β and IL-10 were not significantly different between depression patients and healthy controls." (PMID 37575572, 2023). "Some studies have reported IL-10 levels to be similar in subjects with or without depression; in contrast, a negative correlation between depression score and IL-10 serum concentration was identified through univariate analysis." (PMID 37763079, 2023). "It is noteworthy that in our results, IL-10 produced a small AUC (0.392) for depression prediction, but the 95% CI value did not include 0.5." (PMID 35757220, 2022). "The cytokine IL-10 was found to be significantly correlated with anxiety, depression and average drinks per day but not sleep or the other three drinking variables." (PMID 36032219, 2022).
depression (continued). "To investigate the differences in the expression of inflammatory factors in the serum of normal person, patients with depression, and patients with DCMI, we performed ELISA to detect the levels of NPY, T, IL-1β, IL-6, TNF-α, IL-10, and IL-4 in the peripheral blood plasma." (PMID 35432561, 2022). "Differences in the cytokine profile between BD and MDD were also confirmed by using machine learning—higher levels of IL-10, IL-4 and thiobarbituric acid reactive substances (TBARS) proved to be good at distinguishing between bipolar disorder from unipolar depression." (PMID 36294388, 2022). "The investigation of 38 depression studies found that monocyte-derived, and other inflammatory cytokines (IL-1, IL-4, IL-6, and TNF) were significantly overexpressed in individuals with depression, while T cell derived cytokines (IL-10, and INF-γ) were uncorrelated with depression." (PMID 36206293, 2022). "Most of the inflammatory markers involved in Psoriasis (TNF-α, IL-2, IL-6, IL-23, IL-1β, IL-10), and increased serotonin transporters (5-HTT) were also found in the pathogenesis of depression, showing the immune-inflammatory linkage between psoriasis and major depression." (PMID 34183985, 2021). "In addition, patients with unipolar depression and healthy controls also showed an AUC of 0.74, with 0.69 sensitivity and 0.70 specificity using seven variables (IL-6, carbonyl, BDNF, IL-10, IL-17A, IL-4, and TNF-α)." (PMID 33578686, 2021). "Additionally, given interest in other potential markers of inflammation in relation to depression treatment response, we also explored relationships between several other inflammatory markers including CRP, IL-6, IL-10, TNF-α, and ketamine treatment outcome." (PMID 33723220, 2021). "Besides, MS increased depression and anxiety behavior with an increased level of IL-1β in the ventral hippocampus (vHIP), prefrontal cortex (PFC) and serum, a decreased level of IL-10 in HPV." (PMID 34890365, 2021). "IL-10 in the amygdala and hypothalamus decrease under ELS-induced depression." (PMID 34890365, 2021). "Increased IL-1β, IL-10 and TNF levels are present in patients with depression." (PMID 34610039, 2021). "The final model for hot/coldness in hands/feet included worse fatigue/anxiety/depression (26%), higher pro-inflammatory IFN-γ (18%), worse baseline neuropathy (14%), taxane chemotherapy (11%), lower IL-6 (9%), lower anti-inflammatory IL-10 (9%), and lower BMI (6.5%)." (PMID 34191201, 2021). "The result showed that patients with depression had significantly higher levels of serum IL-6 and IL-6-to-IL-10 ratios compared to patients without depression." (PMID 32235786, 2020). "There is now evidence that major depressive disorder (MDD) is characterized by activation of the immune-inflammatory response system, as indicated by increased levels of pro-inflammatory cytokines including interleukin (IL)-6 and IL-10." (PMID 32093807, 2020). "An increase of two well-known pro-inflammatory cytokines, called interleukin (IL)-1β and tumor necrosis factor-α (TNF-α), as well as a decrease of anti-inflammatory cytokines (e.g., IL-10, IL-4, and TGF-β1) have been observed in hippocampus and cortex of animal models of depression and MDD patients." (PMID 32435223, 2020). "Interestingly, this decrease is accompanied by decreased IL-10 and C-C chemokine ligand 5 (CCL5/RANTES) but increased TNF-α in the PFC in a co-model of pain and depression induced by spinal nerve ligation and olfactory bulbectomy model." (PMID 32849076, 2020). "Similarly, production of IL-6, IL-10, and TNF-α levels have been shown to be increased in animal models for depression using acute or restraint stress, whereas IFN-γ production was significantly decreased by restraint stress in rats." (PMID 30792669, 2019).
depression (continued). "According to the current literature, it seems that peripheral levels of interleukin (IL)-6, IL-10, IL-12, IL-13, and tumor necrosis factor (TNF)-α are elevated and that interferon (IFN)-γ levels are lower in patients with depression compared to healthy controls." (PMID 30792669, 2019). "The domination of M1 phenotype exaggerates neuroinflammation through releasing pro-inflammatory cytokines, such as IL-1β and TNF-α, but suppresses anti-inflammatory cytokines like IL-10 and TGF-β, which may contribute to the etiology of depression." (PMID 30248907, 2018). "In this study, the ratio of IL-6 to IL-10 in the PFC of rats with depression-like phenotype was higher than rats without depression-like phenotype." (PMID 28600519, 2017). "In this study, we observed increased levels of proinflammatory cytokines of IL-6, IL-1β, TNF-α as well as anti-inflammatory cytokines of IL-4 and IL-10 in the rats with depression-like phenotype, but not rats without depression-like phenotype." (PMID 28600519, 2017). "In contrast, there was an increase in IL10 production by CD4 T cells in hip fracture patients with new onset depression compared to hip fracture patients without depression (p = .04) and healthy controls (p = .02)." (PMID 26112234, 2016). "Elevated levels of IL10 mRNA are consistent with previous gene expression studies in patients during a depressive episode, although a meta-analysis suggests that protein concentrations of IL10 do not differ between patients with depression and controls." (PMID 24826212, 2014). "Correlation analysis between HADS score and cytokine levels revealed a positive association of anxiety and/or depression with IL-1β, IL-6, IL-8, and TNF-α and a negative correlation with IL-10." (PMID 25309921, 2014). "Finally, two additional ion channel genes, P2RX1 and TRPV4, as well as two of the genes from our primary analysis, IL-10 and P2RY1, were related to depression severity as assessed by the QIDS and/or HRSD." (PMID 24143878, 2013). "Consistent with previous studies on mRNA in blood of patients with depression, both medication responders and non-responders, we found upregulation in cytokines IL-6 and IL-10 in females with medication-refractory depression." (PMID 24143878, 2013). "The main finding of this study in Caucasian patients is that the proinflammatory cytokines IL-6 and TNFα are not significantly increased and the anti-inflammatory cytokine IL-10 is not decreased in perimenopausal women with depression." (PMID 22490187, 2012). "Taking into account that depression is often associated with hyperactivity of the HPA axis, we hypothesize that IL-10 has a pivotal role in the modulation of the HPA axis homeostasis, which is likely to have an impact on the etiology of depression." (PMID 19936104, 2009). "Future research examining level of depression and inflammatory protein concentrations in serum, saliva, cerebrospinal fluid and neuroimaging may assist in further extrapolating the relationship between TNF-α, IFN-γ, IL-6 and IL-10 and depression." (PMID 39867847, 2025). "However, when patients with depressive disorder were compared with those without depression, significant differences were observed in cytokine response, with higher levels of IL-10, TNF, and TGF-β1 and lower levels of IL-8 for depressive patients." (PMID 40333139, 2025). "Notably, the group with both depressive disorder and chronic T. gondii infection exhibited a distinct cytokine profile characterized by significantly elevated TNF, IL-6, and IL-10 levels and significantly reduced IL-8 and MIF levels compared to the other groups." (PMID 40333139, 2025). "In a model of LPS-induced depression, fluoxetine (20 mg/kg, i.g.)inhibited glial activation, decreasing levels of pro-inflammatory cytokines such as TNF-α, IL-1β, and IL-6, and increasing levels of the anti-inflammatory cytokine IL-10 in the hippocampus of male C57BL/6J mice." (PMID 38474387, 2024).